BCL2 (BCL2 apoptosis regulator)
Diseases named in the same sentence as BCL2 in open-access papers (continued):
Sharing a sentence is not in itself a finding about the gene and the disease.
lung carcinoma (continued). "Three selected tagSNPs of BCL2 (rs2279115, rs1801018, and rs1564483) were genotyped in 1017 paired male Chinese lung cancer cases and controls by TaqMan assay." (PMID 23977251, 2013). "In the study, we designed to investigate the effect of TNF-α on the activation and expression of nuclear factor kappa B (NF-κB)/p65/SLUG/PUMA/Bcl-2 levels in human lung cancer A549 cell line, and in conditions of TNF-α-induced apoptosis." (PMID 23339680, 2013). "Osthole was also shown to induce apoptosis in A549 human lung cancer cells by regulating the expressions of Bcl-2 and Bax." (PMID 24312323, 2013). "Overexpressions of Bcl-2 and Bcl-xl have been demonstrated in a large variety of human malignancies, including breast, prostate, colorectal, and lung cancers." (PMID 23509778, 2013). "It has been proven that most cancers, including lung cancer, generally overexpress Bcl-2, thereby escaping apoptosis and undermining therapy." (PMID 23344197, 2013). "Previous studies have identified bcl-2 expression in human osteosarcoma, lung cancer and metastases, as well as the role of bcl-2 in tumor progression." (PMID 24137369, 2013). "MiR-497 has also been implicated in the development of multi-drug resistance in human gastric and lung cancer cell lines, at least in part, through targeting of anti-apoptotic BCL2." (PMID 23531080, 2013). "Apoptosis has now been widely accepted as a prominent suppression mechanism of lung cancer, and it can be activated through an intrinsic Bcl-2 pathway and an extrinsic death receptor pathway." (PMID 23977251, 2013). "As expected, the expression of both Bax and Bad mRNA increased, but Bcl-2 mRNA was repressed in both lung cancer cells." (PMID 23232551, 2013). "Knockdown of Bcl-2 by siRNA also led to a significant increase in TNF-α-induced apoptosis, consistent with the previous finding that Bcl-2 is the major survival factor in lung cancer cells." (PMID 23339680, 2013). "The role of Bcl-2 in malignant transformation and tumorigenesis was confirmed by gene silencing experiments using human lung carcinoma NCI-H460 cells." (PMID 22666341, 2012). "Some studies have shown that S-nitrosylation of Bcl-2 prevented its ubiquitin-proteasomal degradation and the apoptotic cell death induced by chromium (VI) in lung cancers." (PMID 22629368, 2012). "The inhibition of tumor growth in H460 mutant mice also implicates the general role of Bcl-2 in the tumorigenesis of lung cancer cells." (PMID 22666341, 2012). "Studies done in other cancer cell lines such as lung cancer, gastric cancer, and prostate cancer also showed reduced levels of Bcl-2 after berberine treatment." (PMID 23213296, 2012). "In summary, our results showed that RBM5 significantly inhibits tumor growth and induces apoptosis of lung cancer cells by reducing the expression of Bcl-2, subsequently inducing the expression of cleaved caspase-3, cleaved caspase-9 and cleaved PARP." (PMID 22866867, 2012). "For example, treatment of mice bearing H146 lung cancer xenografts with the Bcl-2 inhibitor ABT-737 leads to transient increases in circulating CK18 and cleaved caspase levels that correlate with treatment and tumour burden." (PMID 22033270, 2011). "Thus, treatment of these lung cancer cells with GSPs can alter the protein levels of key members of the Bcl-2 family in a manner that favors an increase in the ratio of Bax: Bcl-2, which may contribute to the susceptibility of cancer cells to GSP-induced apoptosis." (PMID 22087318, 2011). "Here we studied the level of Bcl-2 expression in lung cancer patients and assessed its prognostic impact on a large cohort of primary NSCLC; our findings were then validated in an independent cohort of 354 NSCLC patients from another continent." (PMID 20459695, 2010). "Trials were selected for further analysis if they provided an independent assessment of Bcl-2 in lung cancer and reported analysis of survival data according to Bcl-2 status." (PMID 12838300, 2003).
lung carcinoma (continued). "Although there are now a large number of studies of Bcl-2 expression, their value in predicting the survival of patients with lung cancer remains controversial." (PMID 12838300, 2003). "We have performed this systematic review of the literature to assess the prognostic value of Bcl-2 overexpression for the survival of lung cancer patients." (PMID 12838300, 2003). "In conclusion, our systematic review of the lung cancer literature suggests that overexpression of Bcl-2, in patients with NSCLC has good prognostic value for survival, whatever the biological test used." (PMID 12838300, 2003). "They all report on the prognostic value for survival of Bcl-2 status in lung cancer patients, assessing Bcl-2 protein expression in the primary tumour." (PMID 12838300, 2003). "Finally, CEBPA binds to Tip60 to promote the transcription of LOXL2 and LOXL3, thereby enhancing the stability of BCL-2 and ultimately promoting the development and metastasis of lung cancer cells." (PMID 41250755, 2025). "S. platensis has been shown to up-regulate the expression of BAX and down-regulate the expression of BCL2 in A549 lung cancer cells, which may contribute to its pro-apoptotic effect." (PMID 41203700, 2025). "However, Bcl-2’s role as a biomarker in lung cancer is more complex and context-dependent than in some other malignancies." (PMID 40841912, 2025). "Thus, CU17 synergized the chemotherapeutic effect of Gem-induced apoptosis via regulating Bax/Bcl-2 signaling in lung cancer A549 cells." (PMID 40006525, 2025). "Therefore, the decreased expression level of Bcl-2 in lung cancer cells after α-MMC intervention exactly explains the phenomenon of depolarization of mitochondrial membrane potential of lung cancer cells, which is consistent with previous results." (PMID 40552155, 2025). "In conclusion, studies have shown that α-MMC mainly inhibits the expression of Bcl-2 through the mitochondrial pathway to activate the Caspase cascade, and significantly induces apoptosis of lung cancer cells through activation of effector protein caspase-3 and induction protein caspase-9." (PMID 40552155, 2025). "Abnormal Bcl-2 expression plays a significant role in lung cancer development and progression by preventing lung cancer cells with irreparable genetic changes from undergoing apoptosis, thereby contributing to their survival and proliferation and potentially leading to tumorigenesis." (PMID 40841912, 2025). "Furthermore, the synergistic impact of Gem and CU4c significantly improved cell cycle arrest during the S and G2/M phases and promoted apoptosis in the human lung cancer cell line via the upregulation of p21, pERK1/2, AcH3, and the Bax/Bcl-2 expression ratio." (PMID 40732250, 2025). "For example, a combination of BCL2 inhibitor Navitoclax with a third-generation EGFR inhibitor osimertinib has demonstrated high safety and feasibility in patients with advanced EGFR-mutated lung cancer." (PMID 39735667, 2025). "Moreover, a comparative analysis revealed that the treatment with RJ and the combination of RJ and AVE resulted in decreased levels of the antiapoptotic protein BCL-2 relative to the pro-apoptotic protein BAX in lung cancer cells." (PMID 39838121, 2025).
lung carcinoma (continued). "This antitumor activity may be achieved by downregulating Bcl-2 and upregulating Bax, suggesting that AP can be used as a potential chemical drug for the clinical treatment of lung cancer." (PMID 39945813, 2025). "Moreover, lung cancer cells in which BCL2 was knocked down became resistant to DC-B01, indicating an on-target effect of DC-B01." (PMID 40113751, 2025). "However, the primary focus in lung cancer research, as in other cancers, is usually on the intracellular expression of Bcl-2 within the tumor cells themselves, as this directly influences their apoptotic machinery." (PMID 40841912, 2025). "NuBCP-9 has been shown to induce Bcl-2-mediated apoptosis in breast and lung cancer cell lines, leading to the hypothesis that it may also reverse Bcl-2-mediated resistance to Tx." (PMID 41114937, 2025). "Additionally, BCL-2 overexpression specifically has been observed to contribute to cisplatin resistance in ovarian and lung cancer." (PMID 40649963, 2025). "Similarly, earlier research has shown that berberine hinders lung cancer cell growth by affecting the matrix metalloproteinase 2 (MMP-2)/Bcl-2/Bax and Janus kinase 2 (Jak2)/vascular endothelial growth factor (VEGF)/NF-κB/AP-1 signaling pathways." (PMID 38334679, 2024). "Similarly, H460 lung cancer cells with high endogenous Bcl-2 expression also showed BH3 domain exposure following treatment with BFC1108 and exhibited responsiveness to BFC1108." (PMID 38329389, 2024). "Moreover, it has been reported that DHA induces apoptosis in the A549 lung cancer cell line, evidenced by an increased Bax/Bcl-2 ratio and elevated levels of active caspase-3 and cytochrome-c." (PMID 38628670, 2024). "Therefore, we attempted to elucidate the mechanism by which circSORBS1 inhibits lung cancer development by regulating the RUFY3/YHWAE/BAD/BCL2 pathway through rescue experiments." (PMID 38915053, 2024). "In this study, we analyzed the relationship between SHMT2, cyclinD1, and Bcl-2 in lung cancer." (PMID 38577602, 2024). "In a lung cancer model, a positive feedback loop was demonstrated between the WT1 and the PI3K/AKT signaling pathway, and loss of WT1 led to decreased proliferation and loss of pAKT as well as decreased expression of antiapoptotic BCL2." (PMID 38190392, 2024). "The results showed that miRNA may be involved in the regulation of several lung cancer driver genes, such as BCL2, CYCS, E2F2, MCL1, or MYC, among others." (PMID 38791013, 2024). "Additionally, mPEG-PLGA-PLL nanoparticles successfully deliver epidermal growth factor (EGF) and Bcl-2-siRNA genes to target H1299 lung cancer cells, resulting in inhibited tumor growth by reducing Bcl-2 expression in tumor tissues." (PMID 38361919, 2024). "Moreover, they stimulate vascular endothelial growth factor A (VEGF-A) and anti-apoptotic factor (B-cell lymphoma-2, Bcl-2) expression, thereby influencing the progression of lung cancer." (PMID 38044948, 2023). "A large number of studies have shown that AS-IV can reduce the level of Bcl-2, promote the expression of Bax, and increase the ratio of Bax/Bcl-2, including that observed in lung cancer, non-small-cell lung cancer, and liver, colorectal, breast, and vulvar cancers." (PMID 36874003, 2023). "Besides, traditional Chinese medicine was found to inhibit the viability of lung cancer cells and induce ferroptosis by promoting Bax via inhibiting BCL2." (PMID 37728703, 2023).
lung carcinoma (continued). "Further, niclosamide was reported to retrieve the sensitivity to radiation of triple-negative breast cancer (TNBC) cell lines via suppression of STAT3 and Bcl-2 and production of ROS, and was also able to overcome radioresistance in human lung cancer cells and in lung cancer xenografts." (PMID 36675241, 2023). "Additionally, the treatment of DH_32 to lung cancer cells resulted in a dose-dependent decrease in the expression level of the anti-apoptotic protein Bcl-2." (PMID 38132948, 2023). "Recently, several studies report that PAIP1 could regulated expression of AKT/GSK-3 β signaling pathway genes in lung cancer, Ki67, Pcna, Bax/Bcl2 and caspase-3 in tongue squamous cell carcinoma, and PLK1 in gallbladder cancer, respectively." (PMID 37101794, 2023). "Besides, exposing lung cancer cells in umbelliferone also lead to activation of caspase-3, decreased expression of BCL-2 and induced cell apoptosis." (PMID 36597133, 2023). "It this context, increases in Bcl-2 protein expression have been shown to contribute to the development of a wide variety of human cancers, including lung cancer, and may act as a resistance factor against several anticancer agents." (PMID 37569812, 2023). "In addition, the overexpression of the Bcl‐2 gene has been detected in non‐small cell lung cancer (NSCLC), and Bcl‐2 protected cancer cells from apoptosis by isolating members of the pro‐apoptotic family and regulating IP3R‐mediated Ca2+ signalling." (PMID 36852470, 2023). "miR-130b overexpression promotes the lung cancer cell progression by PPARγ/VEGF-A/BCL-2." (PMID 35756697, 2022). "A previous study found that ipomoea batatas polysaccharides could induce apoptotic cell death in lung cancer cells via Akt/mTOR-mediated autophagy activation and the autophagic degradation of Bcl-2, a antiapoptotic protein." (PMID 35624772, 2022). "In addition, anti-apoptotic proteins, such as Bcl-2 and Bcl-xl, are highly expressed in lung cancer tissues." (PMID 35631459, 2022). "Moreover, we also found that AOE significantly increased the expression of apoptotic proteins (Bax and Bad) and decreased the expression of anti-apoptotic proteins (Bcl-2) in lung cancer." (PMID 35928278, 2022). "In lung cancer, miR-650 could promote cellular proliferation and invasion, as well as confer the chemoresistance to docetaxel by regulating Bcl-2/Bax expression." (PMID 35996500, 2022). "Additionally, another study revealed that the expression of Bcl2 was negatively correlated with the chemoradioresistance of mesenchymal lung cancer cells." (PMID 35013138, 2022). "In this study, miR-381 mimics could downregulate the expression of USP39 and eventually induce the decrease of the Bcl-2/Bax ratio, control the growth and development of lung cancer cells, and promote the apoptosis of lung cancer cells." (PMID 36046375, 2022). "In addition, S-nitrosylation of an anti-apoptotic protein, B-cell lymphoma 2 (BCL-2), in lung cancer cells also exerts a pro-tumor function." (PMID 33925645, 2021). "Also, CAV1 positively regulates the expression and activity of multiple oncogenic factors, including Akt, CCND1, as well as BCL-2, thus protecting cells from apoptotic cell death in lung cancer." (PMID 33435156, 2021). "At the same time, the β‐elemene upregulates the expression levels of ER‐related proteins, such as ATF6, PERK, IREα, ATF4, and CHOP, and downregulates the expression of Bcl‐2, which inhibits lung cancer growth and cell viability in a dose‐dependent and time‐dependent manner." (PMID 33650320, 2021).
lung carcinoma (continued). "In addition, miR-29 appeared to increase the rate of apoptosis in leukemia, hepatocellular carcinoma (HCC), gastric cancer, lung cancer, and glioblastoma cases through signaling via BCL-2 or myeloid leukemia cell differentiation protein 1 (MCL-1)." (PMID 34445276, 2021). "Therefore, our findings suggest that MS13 mediates the apoptotic activity in NCI-H520 and NCI-H23 lung cancer cells through the activation of caspase-3 and reduction of bcl-2 protein." (PMID 34299042, 2021). "miR-7 targets RAF1, IRS-2, BCL-2, and PA28γ in lung cancer cells." (PMID 33422052, 2021). "Furthermore, β-catenin in the nucleus was almost eliminated by BHGJT, which explained why BCL-2 was downregulated in lung cancer cells." (PMID 34659548, 2021). "In recent studies, overexpression of bcl2 was observed in lung cancer cells." (PMID 33773561, 2021). "We propose that co-targeting Bcl2 and Bak may offer a more effective approach for lung cancer therapy." (PMID 34373755, 2021). "Regarding lung cancer, the chemopreventive role of FX was demonstrated in a mouse model of benzo(A)pyrene-induced lung cancer through apoptosis induction by enhanced caspase 9 and 3 levels and reduced expression of Bcl2 protein." (PMID 34677429, 2021). "Moreover, the expression of Bcl-2 anti-apoptosis protein was significantly decreased in lung cancer cells after treatment with the peptide for 12–24 h compared with non-treated control cells." (PMID 33603033, 2021). "Circ_0014130 can reduce lung cancer cell apoptosis by sponging miR-136-5p and enhancing BCL2." (PMID 34258296, 2021). "PP was also reported to decrease Bcl-2 levels in lung cancer and cervical cancer cells." (PMID 31948057, 2020). "The up-regulation of survival signals and anti-apoptosis proteins regulating both intrinsic (Bcl-2 and Mcl-1) and extrinsic (c-FLIP) pathway is a phenomenon noted in lung cancer specimens and cell lines, causing high resistance to chemotherapy induced-cell death." (PMID 32069989, 2020). "Moreover, our recent work showed that FZKA induced lung cancer cell apoptosis via STAT3/Bcl-2/Caspase-3 pathway." (PMID 32489321, 2020). "Similarly, some studies have shown that activation of STAT3/Bcl-2/caspase 3 signaling can promote apoptosis of NSCLC cells, and acquired resistance of EGFR-mutated lung cancer to TKI treatment is related to the anti-apoptosis effect of the PARP pathway." (PMID 32778129, 2020). "Since CSC treatment downregulates Smad3 by promoting miR-216b expression, we reasoned that induction in miR-216b function might upregulate BCL-2 by reducing Smad3 expression and increase chemoresistance of lung cancer cells." (PMID 32668597, 2020). "Besides, the Bax/Bcl-2 ratio in lung cancer cells was increased by the transfection of miRNA of METTL3, which suggested that apoptosis was inhibited in cancer cells." (PMID 32201509, 2020). "Another study showed that PXN phosphorylation may contribute to cisplatin resistance via the ERK-mediated activation of Bcl-2 transcription in lung cancer." (PMID 33322675, 2020). "RRM2 regulates antiapoptotic protein Bcl-2 in head and neck and lung cancers." (PMID 31886214, 2019).